LDHA (lactate dehydrogenase A)
Diseases named in the same sentence as LDHA in open-access papers (continued):
Sharing a sentence is not in itself a finding about the gene and the disease.
pancreatic cancer (continued). "We investigated whether the PKM2 activator, TEPP-46, and the LDHA inhibitor, FX-11, can be combined to inhibit in vitro and in vivo tumor growth in preclinical models of pancreatic cancer." (PMID 31527446, 2019). "In this study, we investigated whether the PKM2 activator, TEPP-46, and the LDHA inhibitor, FX-11, can be effectively combined to inhibit in vitro and in vivo tumor growth in preclinical models of pancreatic cancer." (PMID 31527446, 2019). "PKM2 and LDHA seem to synergistically catalyze the glycolytic process to promote oncogenic metabolic reprogramming and appear to play a crucial role during the initiation and progression of pancreatic cancer." (PMID 31527446, 2019). "Finally, we analyzed the expressional correlation of EGLN2 with GLUT1, HK2, and LDHA in TCGA pancreatic cancer patients." (PMID 29476053, 2018). "However, inconsistent with our in vitro observations, EGLN2 negatively and significantly correlated with HK2 and LDHA expression in pancreatic cancer patients." (PMID 29476053, 2018). "We postulate that the compromised immune surveillance induced by enhanced expression of PKM2 and LDHA, and reduced CD8+ effector T-cells might be another contributing factor associated with poor prognosis of the glycolytic phenotype of pancreatic cancer." (PMID 26989901, 2016). "In conclusion, we have shown a differential expression pattern for PKM2 and LDHA from cysts through PanIN lesions to pancreatic cancer, with upregulation of LDHA throughout the carcinogenetic process and a progressive upregulation of PKM2 expression along the carcinogenetic pathway." (PMID 26989901, 2016). "Furthermore, a recent study found that FOXM1 played important roles in aerobic glycolysis and tumorigenesis in patients with pancreatic cancer via transcriptional regulation of lactate dehydrogenase A (LDHA) expression." (PMID 27351131, 2016). "The results of our study clearly show up-regulation of both PKM2 and LDHA in pancreatic cancer and implicate the high expression of these two glycolytic enzymes in the development and progression of pancreatic cancer through enhanced proliferation, migration, invasion and angiogenesis." (PMID 26989901, 2016). "However, there are limited data on the expression pattern and prognostic impact of PKM2 and LDHA in pancreatic cancer." (PMID 26989901, 2016). "We then investigated the inhibitory effect of these miRNAs on LDHA in human colorectal caner and pancreatic cancer cell lines, and found that cells stably expressed miR-34a, miR-34c, miR-369-3p, miR-374a and miR-4524a/b decreased the protein level of LDHA in varying degrees." (PMID 26062441, 2015). "Furthermore, deacetylated at lysine 5 (K5) of LDHA by Sirt2 activates LDHA activity, and increases pancreatic cancer cell proliferation and migration." (PMID 26062441, 2015). "Our results demonstrated that LDHA plays a critical role in cancer stemness and gemcitabine resistance of pancreatic cancer, and indicate that targeting the FOXO3a/miR-4259/LDHA pathway might serve as a new treatment for pancreatic cancer patients with a poor response to gemcitabine chemotherapy." (PMID 39930542, 2025). "However, a more extended observation period for survival data, further investigation into the role of LDHA‐dependent effect on tumor‐infiltrating T cells, and evaluating the precise mechanism of berberine in regulating pancreatic cancer remains to be elucidated." (PMID 34185423, 2021). "Therefore, the results suggested that PGK1, ALDOA, and LDHA may play important synergistic roles for P4HA1 in pancreatic cancer." (PMID 33415167, 2020). "Moreover, LDHA has been reported to improve growth and inhibit apoptosis in pancreatic tumor cells." (PMID 32197468, 2020). "Conversely, lysine acetylation inversely regulates LDHA: K5 deacetylation by SIRT2 activates and stabilizes it in pancreatic cancer, while K5 acetylation triggers lysosomal degradation." (PMID 41454479, 2026).
pancreatic cancer (continued). "In pancreatic cancer, activation of c-Myc-lactate dehydrogenase A (LDHA) stimulates glucose utilization, lactate production, proliferation, migration, and invasion of pancreatic cancer cells." (PMID 41584038, 2026). "We further identify that FOXO3a-induced miR-4259 directly targets the 3’untranslated region of LDHA and reduced LDHA expression, leading to decreased gemcitabine resistance and a reduction in the CSC phenotypes of pancreatic cancer." (PMID 39930542, 2025). "Recently, several studies have shown that the transcriptional and post-translational regulation of LDHA by KLF4, FOXM1 and lysine-5 acetylation promotes aerobic glycolysis and the progression of pancreatic cancer." (PMID 39930542, 2025). "H3K18 lactylation in pancreatic cancer cells promotes the expression of TTK/BUB1B kinase, which subsequently upregulates LDHA, leading to increased lactate production." (PMID 40755753, 2025). "Our study specifically analyzed correlations between FOXO3a, miR-4259, LDHA, and CSC markers in pancreatic cancer patients who received gemcitabine treatment." (PMID 39930542, 2025). "In this study, we uncovered a novel mechanism by which miR-4259 is transcribed by FOXO3a and suppresses LDHA expression to inhibit the gemcitabine resistance and CSC properties of pancreatic cancer." (PMID 39930542, 2025). "To characterize the spatial distribution of LDHA and PSMD14, we performed subcellular localization analysis in pancreatic carcinoma cells." (PMID 41051446, 2025). "Conversely, in pancreatic cancer, KLF4 executes an alternative role and inhibits tumor progression by transcriptionally repressing the lactate dehydrogenase (LDHA) enzyme." (PMID 37835497, 2023). "Based on survival analysis, 6 out of 32 MMRGs (LDHA, ALDH3B1, LDHAL6B, PKM, ALDH3A1, and PGAM4) in pancreatic cancer were of survival significance." (PMID 36814901, 2023). "We also found that high levels of DSG2, LDHA, and RACGAP1 predicted poorer overall and disease-free survival in pancreatic cancer patients, although these three genes did not all show good performance in the four validation datasets." (PMID 37391503, 2023). "Based on the protein expression profiles of pancreatic cancer samples collected in the Human Protein Atlas (HPA) database, LDHA, GLS2, and SLC38A10 exhibited higher expression levels in pancreatic cancer." (PMID 37333498, 2023). "Protein levels of GLUT1, PGK1, LDHA, and PKM2 were all decreased by N-methylhemeanthidine chloride (NMHC) in pancreatic cancer cell lines (AsPC-1, BxPC-3, and Mia PaCa-2), resulting in a decrease in glucose metabolism." (PMID 36339566, 2022). "Lactate dehydrogenase A (LDHA), the gene responsible for transcribing M subunits, is upregulated in pancreatic cancer." (PMID 36077352, 2022). "Further, it was connoted that CASC9, a hypoxia-inducible lncRNA, is regulated by HIF-1α and drives glycolysis via the upregulation of hexokinase 2 (HK2), lactate dehydrogenase A (LDHA), and glucose transporter type 4 (GLUT4) levels in pancreatic cancer." (PMID 34298879, 2021). "In pancreatic cancer, FOXM1 promotes aerobic glycolysis and progression by binding directly to the LDHA promoter region and regulating the expression of the LDHA gene." (PMID 34740322, 2021). "FX11 inhibits LDHA by competing with nicotinamide adenine dinucleotide (NADH) and induces oxidative stress and necrosis in human lymphoma and pancreatic cancer xenograft models." (PMID 34540667, 2021). "Our in vitro studies demonstrate that pancreatic cancer cells express both PKM2 and LDHA and that the activity of both enzymes can be effectively altered by TEPP-46 and FX-11." (PMID 31527446, 2019). "In pancreatic tumors and cancer cell lines, FOXM1 and LDHA were found to be overexpressed; increased expression of FOXM1 upregulated LDHA activity and expression at both mRNA and protein level." (PMID 31146503, 2019).
pancreatic cancer (continued). "In pancreatic cancer, KRAS upregulates GLUT1 (glucose transporter 1), as well as HK1 (hexokinase 1), HK2 (hexokinase 2), PFK1 (phosphofructokinase 1) and LDHA (lactate dehydrogenase A), which are key enzymes for the glycolytic processes." (PMID 31225458, 2018). "Genetech Corporation synthesizes another LDHA inhibitor, GNE‐140, a piperidine derivative, which has been shown to effectively inhibit the proliferation of MiaPaCa‐2 pancreatic cancer cells." (PMID 30403008, 2018). "Elevated expression of lactate dehydrogenase A (LDHA) is highlighted in breast and colorectal cancers and has been recently identified in pancreatic cancers." (PMID 28298227, 2017). "The expression pattern in the pancreatic cancer cell lines was similar for both PKM2 and LDHA, except in the KP4 cell line in which the LDHA level was stronger than PKM2 level." (PMID 26989901, 2016). "The levels of HIF-1α were correlated with phosphoinositide-dependent kinase-1, lactate dehydrogenase A and pyruvate kinase, muscle 2 expression and inhibition of HIF-1α repressed pancreatic cancer cell growth." (PMID 26018028, 2015). "In pancreatic cancer cells, FOXM1 binds directly to the LDHA promoter region and activates the expression of LDHA, led to increased cell growth and metastasis." (PMID 26062441, 2015). "Comparing the expression levels between the tissue sections from multiple patients, all pancreatic tumor specimens stained positive for GLUT1, HK2, ENO3, LDHA and PKM2." (PMID 22412968, 2012). "To assess whether inhibiting lactylation could suppress neural invasion in pancreatic cancer, we decreased global lactylation in PANC-1 cells by transfecting siRNAs targeting LDHA and LDHB." (PMID 41356184, 2026). "Consistently, we found that FOXO3a drives miR-4259 expression to target LDHA-3’UTR and decreases LDHA expression and LDH activity in pancreatic cancer, suggesting that the regulation of LDHA is a finely tuned process that helps to balance the entry of pyruvate into aerobic glycolysis." (PMID 39930542, 2025). "Finally, we identified the LDHA as the most potential target from LM.SIG was based on 17 CRISPR datasets, and validated its capacity in pancreatic cancer (PC) via experiments." (PMID 38664705, 2024). "Lactate dehydrogenase A (LDHA), a pivotal glycolytic enzyme, demonstrates upregulated expression across an array of gastrointestinal malignancies, encompassing gastric, esophageal, and pancreatic cancers." (PMID 39184862, 2024). "Finally, we also found that protein levels of DSG2, LDHA, and RACGAP1 were upregulated in pancreatic cancer tissues compared to normal tissues by immunohistochemistry analysis." (PMID 37391503, 2023). "We verified the high expression of PLAU, LDHA, and PKM in pancreatic cancer cells using qPCR in vitro, and we also discovered that the expression of PLAU, LDHA, and PKM in hypoxic pancreatic cancer cells differed from that in normal cultured pancreatic cancer cells." (PMID 37277450, 2023). "Lactate dehydrogenase A (LDHA) converts lactate in pyruvate, and its inhibition impairs invasion and migration in in vitro assays of renal cell carcinoma (RCC), pancreatic cancer and prostate cancer—and decreased metastasis in an orthotopic renal xenograft model." (PMID 36980201, 2023). "We established and validated a telomere gene-related prognostic signature for pancreatic cancer and confirmed the upregulation of DSG2, LDHA, and RACGAP1 expression in clinical samples, which may provide new ideas for individualized immunotherapy." (PMID 37391503, 2023). "In particular, it can lead to the lactylation of histone lysine residues in macrophages to regulate gene transcription Lactate dehydrogenase A (LDHA) is a key enzyme in glycolysis that is highly expressed in various GI tumors, including gastric, esophageal, and pancreatic cancers." (PMID 38041125, 2023).
pancreatic cancer (continued). "We identified PLAU, LDHA, and PKM as key genes involved in pancreatic cancer hypoxia through GO/KEGG enrichment related hypoxia pathways and cox regression, established prognostic models, and studied their relationship to immune invasion through bioinformatics using R and related online databases." (PMID 37277450, 2023). "Graviola, which is extracted from Annona Muricata, could inhibit glucose uptake in pancreatic cancer cells by suppressing the expression of HIF-1α, NF-κB, GLUT1/GLUT4, HK2 and LDHA according to a recent study, thereby decrease ATP generation." (PMID 36339566, 2022). "PI3K inhibitors can inhibit the LDHA-induced activation of the PI3K signaling pathway, which may become a new candidate drug for the treatment of pancreatic cancer." (PMID 34086429, 2021). "In addition, we detected the expression of LDHA and CD163 in pancreatic cancer tissues and paired para-tumor normal tissues by IHC staining." (PMID 34592906, 2021). "It should be noted that although LDHA inhibition plays a critical role in the pancreatic cancer inhibition effect of berberine, it is not the sole mechanism." (PMID 34185423, 2021). "Since LDHA and PKM2, the targets of miR-489-3p are glycolysis-related enzymes, we confirmed that miR-489-3p could inhibit glycolysis of pancreatic cancer cells." (PMID 34868902, 2021). "However, in pre-clinical studies, FX11—a derivative of AT-101 that selectively inhibits LDHA over LDHB—effectively inhibited tumorigenesis in vivo using human lymphoma and pancreatic tumor xenograft models." (PMID 34367959, 2021). "Then, CCK8 and plate cloning assays showed that miR-489-3p could target LDHA and PKM2 to regulate the proliferation of pancreatic cancer cells." (PMID 34868902, 2021). "Similarly, LDHA, EPS8, SLC20A1 and ARNTL2 expression are also related to metastasis or shorter survival in pancreatic cancer." (PMID 32310997, 2020). "In addition, protein levels of lactate dehydrogenase protein isoforms A and B (LDHA, LDHB), key enzymes participating in glucose metabolism and overexpressed in pancreatic cancer were highly expressed in ML and severely down regulated in HS." (PMID 32228510, 2020). "For example, a new study reported that hyperglycemia could enhance glycolysis by increasing LDHA activity and HK2, PFKP expression to promote pancreatic cancer progression." (PMID 31889896, 2019). "Furthermore, LDHA expression has been shown to be stimulated by the nuclear glucose-regulated protein (GRP78)-HIF-1α complex under glucose deprivation, thereby conferring GEM resistance in pancreatic cancer." (PMID 40264038, 2025). "We further used our clinical pancreatic cancer specimens to analyzed the LDHA levels in pancreatic cancer patients receiving treatment with gemcitabine and observed that patients with better overall-survival (OS) and recurrence-free survival (RFS) showed lower level of LDHA expression." (PMID 39930542, 2025). "Notably, although cell‐based experiments indicated that PSMD14 does not affect LDHA transcription, TCGA database analysis revealed a significant positive correlation between their mRNA levels in pancreatic cancer tissues." (PMID 41051446, 2025). "It was found that overexpression of FBW7 in pancreatic cancer cells activates the c-Myc signaling pathway to target thioredoxin-binding protein (TXNIP), a negative regulator of glucose metabolism, which in turn inhibits glycolysis-related genes, including GLUT1, GLUT4, HK2, LDHA and LDHB." (PMID 37152291, 2023).
pancreatic cancer (continued). "Selected hits block lactateproduction in cells and inhibit pancreatic cancer cell lines withcytotoxicity IC50 down to 12.26 μM against MIAPaCa-2cells and 14.64 μM against PANC-1, which, under normoxic conditions,is already comparable or more potent than most currently availableknown LDHA inhibitors." (PMID 36646658, 2023). "We established and validated telomere gene-related prognostic features in pancreatic cancer and confirmed the upregulation of DSG2, LDHA, and RACGAP1 expression in clinical samples, which may provide new ideas for individualized immunotherapy targeting telomere genes." (PMID 37391503, 2023). "For instance, high LDHA levels in serum could be a negative prognostic biomarker in osteosarcoma, pancreatic cancer, and lung adenocarcinoma." (PMID 31737570, 2019). "Moreover, K5 acetylation of LDHA is reduced and accompanied by increased LDHA protein levels in early and late stages of pancreatic cancers, which suggests a possible role of K5 acetylation in pancreatic cancer initiation, but not progression." (PMID 31035592, 2019). "Unlike TES, LDHA together with KLF4 or c-Myc has been found to positively regulate aerobic glycolysis and promote tumor progression in pancreatic cancer." (PMID 35789607, 2022). "All human pancreatic cancer cell lines analyzed expressed both PKM2 and LDHA at both proliferative and nonproliferative stages of cell culture." (PMID 31527446, 2019). "However, there is a negative correlation between KLF4 and LDHA expression in pancreatic cancer cells, and KLF4 binds directly to the promoter regions of the LDHA gene and negatively regulates its transcription activity." (PMID 26062441, 2015).